Y_RNA (Y RNA )
Gene: Miscellaneous RNA gene on chromosome 3 (47,931,808 to 47,931,914, reverse strand). Ensembl gene ENSG00000199591.
Homologues: Orthologues: chimpanzee Y_RNA (99% identical), macaque Y_RNA (97% identical), guinea pig Y_RNA (87% identical), guinea pig Y_RNA (86% identical). Paralogues in human: Y_RNA (91% identical), RNY1 (90% identical), Y_RNA (89% identical), Y_RNA (88% identical), Y_RNA (87% identical), RNY1P11 (86% identical), Y_RNA (86% identical), Y_RNA (85% identical), RNY1P8 (84% identical), Y_RNA (84% identical), Y_RNA (83% identical), Y_RNA (82% identical), and 99 more.